MS4A2 (membrane spanning 4-domains A2)
Description:
High affinity receptor that binds to the Fc region of immunoglobulins epsilon. Aggregation of FCER1 by multivalent antigens is required for the full mast cell response, including the release of preformed mediators (such as histamine) by degranulation and de novo production of lipid mediators and cytokines. Also mediates the secretion of important lymphokines. Binding of allergen to receptor-bound IgE leads to cell activation and the release of mediators responsible for the manifestations of allergy.
Synonyms: FcERI; APY; FCER1B; IGER; ATOPY; IGEL; IGHER
Tractability: Small molecule: a structure with a bound ligand is known. Antibody: its Gene Ontology location is reachable by antibodies, with high confidence; UniProt predicts a signal peptide or a membrane-spanning region.
Gene: Protein-coding gene on chromosome 11 (60,088,261 to 60,098,467, forward strand). Ensembl gene ENSG00000149534.
Subcellular location: Membrane
Pathways (Reactome):
Immune System: FCERI mediated Ca+2 mobilization; FCERI mediated MAPK activation; FCERI mediated NF-kB activation; Fc epsilon receptor (FCERI) signaling; Role of LAT2/NTAL/LAB on calcium mobilization
Gene Ontology:
Molecular function: protein binding; IgE binding
Biological process: immune response; cell surface receptor signaling pathway
Cellular component: external side of plasma membrane; Fc-epsilon receptor I complex; plasma membrane; membrane
Genetic constraint (gnomAD): Loss-of-function variants: 20 observed, 24.65 expected, observed/expected ratio (o/e) 0.81, 90% interval 0.57 to 1.18. The upper end of that interval is the gene's LOEUF score, 1.18, which puts it in group 5 of 6, group 1 being the genes least tolerant of losing a copy. Missense variants: 250 observed, 254.96 expected, observed/expected ratio (o/e) 0.98, 90% interval 0.88 to 1.09. Synonymous variants: 95 observed, 90.42 expected, observed/expected ratio (o/e) 1.05, 90% interval 0.89 to 1.25.
Homologues: Orthologues: chimpanzee MS4A2 (98% identical), macaque MS4A2 (89% identical), dog MS4A2 (63% identical), rabbit MS4A2 (59% identical), pig MS4A2 (59% identical), mouse Ms4a2 (58% identical), guinea pig MS4A2 (56% identical), rat Ms4a2 (55% identical), zebrafish ms4a17a.5 (20% identical), zebrafish si:dkey-77f5.10 (20% identical), zebrafish ms4a17a.10 (19% identical), zebrafish ms4a17a.12 (19% identical), and 21 more. Paralogues in human: MS4A4A (25% identical), MS4A15 (22% identical), MS4A14 (21% identical), MS4A3 (20% identical), MS4A8 (20% identical), MS4A7 (20% identical), MS4A12 (19% identical), MS4A6A (19% identical), MS4A10 (18% identical), MS4A4E (18% identical), MS4A1 (17% identical), MS4A5 (16% identical), and 4 more.
Diseases named in the same sentence as MS4A2 in open-access papers:
MS4A2 is named in the same sentence as 29 diseases in open-access papers, as found by Europe PMC text mining. Sharing a sentence is not in itself a finding about the gene and the disease. The quoted sentences say what the papers report.
asthma (26 papers, 2006 to 2025). "On the contrary, the posterior that, rs569108 in MS4A2 is transitively associated with asthma is 0.633, but the posterior for a “direct” relation is only 0.087." (PMID 22432035, 2012). "These analyses suggested that SNPs in the AHNAK and MS4A2 genes were indirectly associated with asthma." (PMID 22432035, 2012). "All of the MS4A2 SNPs evaluated were associated with a lower odds of asthma, and the associations were statistically significant for rs556917 A/T, rs502581 C/A, and rs502419 G/A." (PMID 21320344, 2011). "In addition to its role in amplifying IgE-mediated mast cell activation, polymorphisms in the gene encoding FcεRIβ, MS4A2, have been linked to allergy and asthma susceptibility, suggesting a potential role for FcεRIβ in development of allergy." (PMID 35054974, 2022). "Recently, a study has shown that the MS4A2 (membrane-spanning 4 domains, superfamily A, number 2) gene is located on chromosome 11q13, a region that is linked to asthma-related phenotypes, and it plays an important role in the regulation of human mast cell proliferation and survival." (PMID 36146599, 2022). "Finally, in the asthma vs. HC comparison, 9 SNPs were identified, with 2 associated with risk in the MS4A2 gene (rs573790 p = 0.001, OR = 1.70, CI 95% = 1.21-2.37), and 7 SNPs associated with protection in 4 genes (TBXAS1, FANCC, CYSLTR2, and PTGER3)." (PMID 30254660, 2018). "In this study, we have comprehensively analyzed the association of 286 common variants of eight candidate genes with asthma and atopic asthma in a case-control Spanish sample and found associations for 10 SNPs in three of them (MS4A2, IL4R and ADAM33) after considering all tests performed." (PMID 24039878, 2013). "Associations were confirmed between SNPs in PTGDR, PTGER2, MS4A2 and asthma." (PMID 22432035, 2012). "The explanation for this phenomenon is, that according to our evaluation, SNPs in the PTGER2 influence asthma susceptibility in interactions or indirectly, and similarly, the association between a SNP in MS4A2 and asthma is transitive, which is hard to detect with traditional frequentist methods." (PMID 22432035, 2012). "State 1 was defined as asthma-related eosinophils predominantly found in the asthma model, including the following genes: H2Aa, Ms4a2, Fcer1g, and Rpl10." (PMID 37816708, 2023). "For TBXAS1 rs757760, MS4A2 rs502581, IL10 rs3024498, and ACE (rs4293 and rs4309), we did not detect any statistical association comparing AERD vs. asthma/HC or asthma vs. HC, in the allelic, recessive and codominant models (p > 0.05)." (PMID 30254660, 2018). "This gene set includes numerous cytokines that mediate Th2 cell signaling associated with asthma (IL3, IL4, IL5, IL9, IL10 and IL13), as well as components of the IgE receptor (FCERA, FCERG, MS4A2) and eosinophil granule proteins (ECP, EDN, EPX, and MBP)." (PMID 28854632, 2017). "Our results support the important role of MS4A2, IL4R and ADAM33 genes in asthma and/or atopy susceptibility." (PMID 24039878, 2013). "We found that variants at MS4A2, IL4R and ADAM33 genes demonstrated varying association effects with the age at diagnosis of asthma, with 10 SNPs showing study-wise significance after the multiple comparison adjustment." (PMID 24039878, 2013). "Statistically significant associations with asthma were observed for SNPs in GSTM1, MS4A2, and GSTP1 genes, after correction for multiple testing." (PMID 21320344, 2011). "Statistically significant associations were only observed for the asthma phenotype, for SNPs in GSTM1, MS4A2, and GSTP1, after correction for multiple testing." (PMID 21320344, 2011). "This study evaluated 8 of these genes (IL4, IL13, TNF-α, HLA-DRB1, HLA-DQB1, FCER1B/MS4A2, CD14, ADAM33) as well as 3 glutathione-s-transferase genes (GSTM1, GSTP1, and GSTT1) for association with asthma/allergy among urban-residing African Americans." (PMID 21320344, 2011).
asthma (continued). "In addition to many important asthma-related genes identified in the current study, basophil-specific gene signatures, such as Mcpt8, Ms4a2, Cpa3, Fcer1a, and Cd200r3 were highly expressed in the AM group." (PMID 40443683, 2025). "The clinical benefits of targeting FcεRIβ have been ambiguous, since the association of MS4A2 polymorphisms with allergy and asthma is not consistent and transfection of MS4A2 cDNA containing mutations associated with asthma has previously failed to alter FcεRIβ function." (PMID 35054974, 2022). "We also found enrichment of the asthma pathway using the KEGG database (corrected P = 4.80 × 10− 3), containing MS4A2 and genes in HLA." (PMID 29566699, 2018). "MS4A2 (FCER1B) plays a role in allergic or autoimmune diseases, such like Wegener's granulomatosis, asthma and atopic dermatitis." (PMID 23515576, 2013). "We compared the gene expression levels of genes found to be relevant in asthma in the SNP analysis in sputum samples of 12 asthmatics and 9 controls using TaqMan Gene Expression Assays (FRMD6, PTGDR, PTGER2, MS4A2, AHNAK, PRPF19, TXNDC16)." (PMID 22432035, 2012). "For allergic diseases and asthma, FcεRIβ is an ideal target for SSO therapy, since it has a characteristic role in IgE-mediated mast cell activation that is inhibited by SSO-mediated alternative splicing of the MS4A2 gene." (PMID 35054974, 2022). "Before the advent of genome-wide association studies (GWAS), ADAM33, ADRB2, CD14, MS4A2 (alias FCER1B), IL13, IL4, IL4R, and TNF constituted the most replicated non-HLA candidate genes with asthma and related traits." (PMID 24039878, 2013).
Allergy (14 papers, 2010 to 2025). An allergy is an immune response or reaction to substances that are usually not harmful. "Another example, MS4A2, encodes the beta subunit of the high affinity IgE receptor which is involved in allergic reactions." (PMID 39680574, 2024). "The dual role of MS4A2 (rs569108) in vitamin D-dependent allergy modulation refines our understanding of genetic regulation in IgE-mediated responses." (PMID 40927566, 2025). "Thus, altered splicing of MS4A2 could have implications in susceptibility to allergic diseases." (PMID 35054974, 2022). "The same finding applies to IgE receptor activation (FCER1G, MS4A2), which is mainly triggered by the presence of parasites or bacteria and connected to allergy response." (PMID 30509175, 2018). "MS4A2 gene codifies the beta subunit of the high-affinity IgE receptor, involved in allergy and parasites immunity." (PMID 27624002, 2016). "Furthermore, a two-sample MR approach leveraging large GWAS and eQTL databases suggested a potential causal role for IL4, IL1RL1, RP11-13A1.1, FCER1A and MS4A2, RUNX1, and ACLS6 expression in various allergic diseases and serum IgE levels." (PMID 36725846, 2023). "Indeed, a Mendelian randomization approach based on GWAS summary statistics indicates that several of these genes, including interleukin-4 (IL4) and IgE receptors (FCER1A, MS4A2), affect the incidence of allergic diseases." (PMID 36725846, 2023). "MS4A2 gene (earlier known as FcεRI-β), which codes for the high affinity IgE receptor β subunit has a central role in mast cell degranulation and IgE mediated allergy." (PMID 22432035, 2012). "MS4A2 (FcRβ) is a signaling subunit of the high affinity IgE receptor (FcεRI) and the low affinity IgG receptor (FcγRIII) on mast cells, and therefore has a key role in hypersensitivity and allergic reactions." (PMID 20186339, 2010).
autoimmune disease (2 papers, 2013 to 2022). A disorder resulting from loss of function or tissue destruction of an organ or multiple organs, arising from humoral or cellular immune responses of the individual to their own tissue constituents. "Specific functions have been described for 3 members of the family (MS4A1/CD20; MS4A2; MS4A4A) and MS4A1/CD20 has proven to be an invaluable therapeutic target for the treatment of B cell malignancies and autoimmune diseases." (PMID 34346525, 2022).
eczema (2 papers, 2021). "Our study is the first to report an independent association of MS4A2 rs569108 GG homozygote with eczema in two-year-old children." (PMID 34261469, 2021). "How the polymorphism in the MS4A2 gene interacts with antibiotic exposure in early life to increase risk of eczema remains unknown." (PMID 34261469, 2021).
lung adenocarcinoma (2 papers, 2023 to 2025). A carcinoma that arises from the lung and is characterized by the presence of malignant glandular epithelial cells. "According to the Kaplan-Meier curve, patients with lung adenocarcinoma having poor expression of MS4A2, MS4A7, MS4A14, and MS4A15 had a low overall survival rate." (PMID 37533433, 2023). "In this study, four key biomarkers closely related to mesenchymal stem cell proliferation/differentiation (MSCPD) were identified in lung adenocarcinoma (LUAD), namely MS4A2, IGSF10, NTRK3, and MFAP3L." (PMID 40598621, 2025).
atherosclerosis (1 paper, 2024). A disease characterized by the build-up of fatty material and calcium deposition in the arterial wall resulting in partial or complete occlusion of the arterial lumen. "Among major findings, our results suggest a role of triglyceride-associated and mast-cell functional genes FCER1A, MS4A2, GATA2, HDC, and HRH4 in atherosclerosis risks." (PMID 39276247, 2024).
leukemia (1 paper, 2022). A malignant (clonal) hematologic disorder, involving hematopoietic stem cells and characterized by the presence of primitive or atypical myeloid or lymphoid cells in the bone marrow and the blood. "T-cell populations from vehicle treated mice with leukemia exhibited significant upregulation of genes associated with immune exhaustion, such as Lag3, Tigit and Il10, as well as Ms4a2, an immune suppressive gene expressed by T-regulatory cells." (PMID 35831470, 2022).
lung carcinoma (1 paper, 2025). "Generally, our study identified two important prognostic mRNAs (MS4A1, MS4A2) that were significantly altered between high- and low-risk patients with lung cancer and developed a risk model independent of the clinical factors." (PMID 40053252, 2025).
preeclampsia (1 paper, 2022). Preeclampsia is a hypertensive disorder of pregnancy that is characterized by new-onset hypertension with proteinuria presenting after 20 weeks of gestation, and depending on mild or severe forms may initially present with severe headache, visual disturbances, and hyperreflexia. "Among these genes, we screened the key gene MS4A2 most related to preeclampsia through the database and clinical data validation." (PMID 35782866, 2022). "In this study, we also identified MS4A2 in peripheral blood as a biomarker highly correlated with the onset and severity of preeclampsia." (PMID 35782866, 2022). "All the three gene expressions decreased significantly in the preeclampsia group, but only the level of MS4A2 was related to the severity of the disease." (PMID 35782866, 2022). "Finally, it was confirmed in the collected clinical peripheral blood samples that MS4A2 was differentially expressed in the peripheral blood of early-onset and late-onset preeclampsia, which is of great significance." (PMID 35782866, 2022). "This study showed that the expression of MS4A2 in the peripheral blood of patients with preeclampsia during early pregnancy was significantly lower than that of normal pregnant women, which also confirmed the role of mast cells in the pathogenesis of preeclampsia." (PMID 35782866, 2022). "Finally, in the test cohort of clinical peripheral blood samples, the differential expression of three genes in preeclampsia peripheral blood was verified again, and MS4A2 was confirmed to be the only gene marker with a statistical difference between early-onset and late-onset preeclampsia." (PMID 35782866, 2022). "Independent studies between the two samples showed that there were three genes with reduced expression and statistical differences in preeclampsia: SLC18A2, HDC, and MS4A2." (PMID 35782866, 2022).
vitamin D deficiency (1 paper, 2025). A nutritional condition produced by a deficiency of VITAMIN D in the diet, insufficient production of vitamin D in the skin, inadequate absorption of vitamin D from the diet, or abnormal conversion of vitamin D to its bioactive metabolites. "Unlike the uniformly risk-amplifying effects of Th2-pathway variants (IL4R/IL-4/IL13) under vitamin D deficiency, MS4A2’s role is protective and vitamin D-dependent." (PMID 40927566, 2025).
tumor (9 papers, 2020 to 2025). "Furthermore, expression of the high-affinity IgE receptor gene MS4A2 by tumour-infiltrating mast cells in lung cancer was associated with a favourable prognosis and correlated with innate anti-tumour immune responses." (PMID 32695309, 2020). "MS4A2 has emerged as an independent prognostic factor in LUAD, even in early stages, potentially linked to mast cell activity within the tumor microenvironment." (PMID 40598621, 2025). "MS4A2, an IgE receptor related gene expressed in tumor-infiltrating mast cells, was an independent favorable prognostic biomarker." (PMID 34745939, 2021). "HOXC8 is localised in the cytoplasmic of tumour cells, and MS4A2 is expressed in interstitial cells." (PMID 33557848, 2021). "Furthermore, MS4A2 represents a promising autonomous prognostic factor and therapeutic target for enhancing anti-tumor immunity, especially in early-stage disease." (PMID 40598621, 2025). "Among them, BNC2, SYNM, and TCF21 target genes were detected in all tumor locations, and three targets (GRIK2, KLHL14, and MS4A2) were shared by R-CRC and L-CRC but not by RC." (PMID 37987361, 2023).
cancer (6 papers, 2020 to 2025). A tumor composed of atypical neoplastic, often pleomorphic cells that invade other tissues. "Numerous studies have underscored the prognostic relevance of MS4A2 across various cancers, including gastric, colorectal, and LUAD." (PMID 40598621, 2025). "At both the mRNA level and the protein level, the levels of ZBTB7C, TPSB2, MS4A2, CD19, and MS4A1 in CRC tissues were lower than those in normal tissues adjacent to the cancer." (PMID 33946045, 2021).
MS4A2 also shares sentences with these, for which no sentence is quoted: allergic asthma (2 papers); allergic rhinitis (2); glioma (2); melanoma (2); Alzheimer disease (1); atopic allergy (1); atopic asthma (1); atopic dermatitis (1); diabetes (1); gastric cancer (1); Hypertension (1); ischemic stroke (1); lung disease (1); nasal polyps (1); Respiratory Disease (1); rheumatoid arthritis (1); Wegener's granulomatosis (1).